PARP1 (poly(ADP-ribose) polymerase 1)
Diseases named in the same sentence as PARP1 in open-access papers (continued):
Sharing a sentence is not in itself a finding about the gene and the disease.
cancer (continued). "While extensive research in recent years has primarily focused on PARP1 and its immunoregulatory effects, the spotlight is increasingly turning to other ARTs that play important roles in modulating immune responses and may offer new avenues for cancer therapy." (PMID 39062190, 2024). "Hence, the development of PARP-1 inhibitors has acquired importance since it has been demonstrated that this kind of molecules could induce cell death in cancer cells." (PMID 38255943, 2024). "Previously, we discovered that the simultaneous absence of XRN2 and PARP1 compromises the survival of non-cancer and cancer cells; however, the underlying cellular stress response remained unknown." (PMID 38339346, 2024). "Consequently, PARP1 inhibition induces synthetic lethality in BRCA1/2-mutant cancer cells." (PMID 39318358, 2024). "PARP1 inhibitors can induce synthetic lethality in cells lacking in homologous recombination capabilities and have been approved for the treatment of several cancers with these deficiencies." (PMID 39796080, 2024). "However, the mechanism by which cancer cells overcome PARP1 trapping to develop PARPi resistance remains unclear." (PMID 38973255, 2024). "Collectively, these findings suggest that loss of PARP1 replication activity due to PARPi, PARP1 deletion or FANCJ loss is toxic to BRCA1 deficient cells predicting that PARPi efficacy in BRCA mutant cancer derives from loss of PARP1 S-phase activity and not PARP1 trapping." (PMID 38521768, 2024). "Finally, these cells appear to be heavily dependent on PARP1/2 for DNA repair and treatment with the PARP1/2 inhibitor Olaparib results in synthetic lethality, suggesting that low KMT2C-expressing cancer cells are an attractive target for PARP1/2 inhibitor therapy." (PMID 39165358, 2024). "Furthermore, PARP1 has also been found to play a role in transcriptional regulation, chromosome stability, cell division, differentiation, apoptosis, and has been considered the most actively-pursued target for treating some cancers." (PMID 38582911, 2024). "Moreover, unligated Okazaiki fragments, on which PARP1 may be trapped, can be converted into structures that result in synthetic lethality in HR-defective cancer cells." (PMID 38578205, 2024). "Therefore, targeting PARP1 by carnosol administration could be a potential therapeutic strategy for cancer treatment." (PMID 38806527, 2024). "PARP inhibitors that target PARP1/2, such as olaparib and talazoparib, have been approved as anticancer agents for patients with breast and ovarian cancers bearing mutations in the homologous recombination (HR) factors BRCA1 and BRCA2, as well as for platinum-sensitive cancers." (PMID 38625917, 2024). "Four PARP inhibitors (PARPi) that are blocking the activity of PARP1/2 and are trapping PARP1 on the chromatin have been clinically approved for the treatment of breast (olaparib, talazoparib), ovarian (olaparib, niraparib, rucaparib), prostate (rucaparib), and pancreatic (olaparib) cancer." (PMID 38360994, 2024). "Thus, The GL methodology aims to facilitate preclinical drug discovery for target and tool development to probe cancer biology and the mechanism for undruggable proteins and multifunctional complexes (out of our protein targets, only PARP1 is a clinically validated target)." (PMID 39669672, 2024). "Moreover, the role of PARP-1 in regulating fork speed was recently demonstrated in cancer cells." (PMID 39201718, 2024). "Thus, PARP1 inhibitors are still ineffective in the treatment of some cancer patients." (PMID 39679370, 2024). "Thus, HR-deficient cancer cells exhibit superior susceptibility to PARP1 inhibitors due to their involvement in non-HR repair mechanisms." (PMID 37834477, 2023). "Moreover, it seems as if there is a lack of specificity to target cancer cells versus normal cells unless the tumours are sensitised to PARP-1 inhibition because of deficiencies in DNA repair or specific genetic background." (PMID 37686260, 2023).
cancer (continued). "Therefore, PARP-1 is considered an ideal target for cancer chemotherapy." (PMID 37891641, 2023). "However, since PARP1 is involved in non-HR repair, HR deficient cancer cells are extremely vulnerable to PARP1 inhibitors." (PMID 36909172, 2023). "Hence, taken together, we believe that high expression of C12orf48 could be a prognostic marker in cancer cells, and knockdown of C12orf48 might be a solution to attenuate the ability of PARP1 and preserve genomic stability." (PMID 35100974, 2022). "Hence, the PARP1-MGMT protein complex could be targeted for the development of advanced and more effective cancer therapeutics, particularly for cancers sensitive to PARP1 and MGMT inhibition." (PMID 36242092, 2022). "Thus, we hypothesized that mRNA levels corresponding to proteins that co-occupy stressed replication forks with PARP1 may serve as a proxy for the dependency of cancer cells on PARP-dependent replication fork protection." (PMID 36350633, 2022). "However, which specific signal pathway and related mechanism that trigger PARP1 hyper-activation and parthanatos in cancer remains unknown." (PMID 35715817, 2022). "Furthermore, our study lays a foundation for future exploration into whether PARP1 inhibitor treatment might provoke inflammatory signaling and enhance immune checkpoint inhibitor treatment in BER deficient cancer patients." (PMID 36624848, 2022). "Interestingly, we observed a lower expression of cleaved PARP-1 and ARP2/3 in the hepatocytes of metastatic lesions that were generated from RUNX1-deficient HT29 cancer cells in comparison to those that were generated by control HT29 cancer cells." (PMID 35267627, 2022). "Therefore, PARP1 inhibitors are widely used for anti-cancer treatment." (PMID 36091054, 2022). "Further in vitro experiments showed that TAX could significantly induce cancer cell apoptosis as verified by increased pro-apoptotic molecules including Bax, caspase-9, and PARP1 downregulated anti-apoptotic protein Bcl-2; and decreased mitochondrial potential." (PMID 36230568, 2022). "In addition to provoking cell death, which triggers inflammatory reactions by multiple mechanisms, extensive and sustained activation of PARP1 in cancer cells was documented to promote glycolysis and exacerbate inflammation, 2 key components in the initiation and progression of RV failure." (PMID 35540097, 2022). "Finally, in silico analysis demonstrated binding of compound 5s towardsthe catalytic site of PARP-1, indicating that these novel oxadiazoles synthesized herein may serve as exemplars for the development of new therapeutics in cancer." (PMID 35163965, 2022). "However, HR-deficient cells lacking BRCA1 or BRCA2 show specific susceptibility to PARP1 inhibition, whereby accumulation of genetic lesions and ensuing chromosome instability in fast-dividing cancer cells results in their death." (PMID 35018214, 2022). "Therefore, it is not surprising that dysregulation of PARP-1 is associated with chronic inflammatory diseases as well as cancers." (PMID 35158955, 2022). "In addition, a pan-cancer study highlighted that altered PARP1 was correlated with the high degree of immune cell infiltrations, such as CD8+ T cells, in most cancers, simultaneously, there were higher expression levels of PD-1, LAG3, and CTLA-4 in the PARP1-altered group." (PMID 36818471, 2022). "Therefore, the establishment of an epigenetic mark, such as DNA methylation, in normal and cancer cells might occur through PARP1’s regulation." (PMID 33804735, 2021). "Thus, the effect of PARP1-mediated DNA repair on cancer suppression and progression may be dependent on the cellular context." (PMID 34830134, 2021). "Hence, PARP1 inhibitors have achieved major clinical successes in the treatment of cancers with defects in the Homologous Recombination DNA repair pathway associated with BRCA1 and BRCA2 mutations or when combined with traditional DNA damaging agents such as chemotherapy and/or radiotherapy." (PMID 34207240, 2021).
cancer (continued). "Consequently, PARP1 has emerged as an attractive target for cancer therapy." (PMID 34445442, 2021). "Targeting mediators of microhomology-mediated end joining (MMEJ) POLQ and PARP1 also had a statistically significant viability reducing and DNA damage increasing effect on the cells supporting the concept of synthetic lethality of POLQ (polymerase theta, Polθ) inhibition in HR deficient cancers." (PMID 34084283, 2021). "Interestingly, investigating on CENPB protein interactors, the results associated not only with other proteins involved in centromere formation, but also with PARP1 which is known to be involved in programmed cell deaths, in cancer, and in the cellular response to DNA damage." (PMID 34439361, 2021). "Our results highlight the significance of PARP1 alterations as pan-cancer predictive biomarkers for ICI treatment, and its expression levels seem to be correlated with the status of immunotherapy-associated signatures, thus may be a promising biomarker for predicting ICI response in several tumors." (PMID 34531868, 2021). "In addition, several studies concluded that the repression of parp-1 could be an interesting approach to develop synthetic lethality in cancer cells and in the regulation of the anti-inflammatory response." (PMID 33809299, 2021). "To illustrate the flexibility of CanDI to mine context-specific synthetic sick lethal (SSL) genetic relationships, we hypothesized that the genes that modulate response to a PARP1 inhibitor might be enriched for selectively essential proliferation or survival of BRCA1-mutant cancer cells." (PMID 34663427, 2021). "Furthermore, we demonstrate that MortaparibPlus-induced cytotoxicity to cancer cells is mediated by multiple mechanisms that included the inhibition of PARP1, up-regulation of p73, and also the down-regulation of mortalin and CARF proteins that play critical roles in carcinogenesis." (PMID 33671256, 2021). "However, the role of PARP1 alteration across cancers remained unclear." (PMID 34531868, 2021). "Thus, PARP1 inhibitors are promising and have been applied to cancer treatment." (PMID 33495407, 2021). "The cancers that have existing deficiencies in DNA repair machinery, such as those with BRCA1/2 mutations or PTEN dysfunction, are particularly vulnerable to PARP inhibition because they rely more heavily on the single-strand break repair pathway in which PARP1 is a critical component." (PMID 34610973, 2021). "This suggests that a correct dosage of HPF1 is important for proper balancing of various PARP1- and PARP2-catalysed reactions, and therefore subtler changes beyond simple loss-of-function might also be of therapeutic relevance in both cancer and other diseases." (PMID 34210965, 2021). "However, despite a great interest in PARP1 as a target for cancer therapy and the arising therapeutic potential of PARG inhibition, the relative contribution of ARH3 and PARG in regulating the levels of ADPr in human cells remains unclear." (PMID 34019811, 2021). "Therefore, the activation of PARP1 through H2S mediated signaling may help to promote damaged cancer cell survival during cancer development." (PMID 34207284, 2021). "Furthermore, PARP1 inhibitors have become increasingly important in the field of cancer treatment." (PMID 34199353, 2021). "Similar to BRCA1/2-deficient cancers, mutation in the BAP1 gene leads to homologous recombination-deficient (HRD) tumors and increases the reliance on poly ADP ribose polymerase (PARP)-mediated DNA repair pathways; therefore, PARP1/2 inhibitors can induce synthetic lethality in MPM." (PMID 34070352, 2021). "As expected, miR-155-5p ectopic overexpression followed by Olaparib administration resulted in a greater reduction of cell viability as compared to Olaparib administration alone, suggesting that miR-155-5p might induce a synthetic lethal effect in cancer cells when coupled with PARP-1-inhibition." (PMID 32903519, 2020).
cancer (continued). "Interestingly, a significant proportion of poly(ADP-ribose) polymerase 1 (PARP1) molecules are localized in the nucleolus and PARP1 also plays crucial roles in many processes that are important in cancer biology, including genome maintenance, replication, transcription, and chromatin remodeling." (PMID 32640701, 2020). "In addition, preclinical and clinical studies have shown that PARP-1 activity in cancer cells is critical for the establishment of resistance to genotoxic therapies, suggesting that there is a real opportunity to combine PARPi with chemotherapy and radiotherapy." (PMID 32029902, 2020). "Thus, inhibition of DNA damage response (DDR) mechanisms, especially with PARP1 depletion in BRCA1/2‐deficient models, may decrease the survival of cancer cells and promote a more effective antitumour therapy." (PMID 32686903, 2020). "Therefore, functional interplay between PARP1 and YB-1 may affect the application of PARP1 inhibitors in cancer treatment." (PMID 32947956, 2020). "We provide experimental evidences that (i) Wi-A and CAPE cause inactivation of PARP1-mediated DNA repair leading to accumulation of DNA damage and activation of apoptosis signaling by multiple ways, and (ii) a combination of Wi-A and CAPE offers selective toxicity and better potency to cancer cells." (PMID 32380701, 2020). "And PARP1 inhibition-induced inhibition of HIF-1 α might contribute to cancer cell death." (PMID 33665167, 2020). "Hence, the down-regulation of PARP-1 by HT would be potentially beneficial in cancer patients, e.g. it could counteract the cardiovascular and musculoskeletal complications associated to anti-cancer therapies." (PMID 32286485, 2020). "Moreover, as a result of PARP1 inhibition, cancer cells may upregulate the HR repair pathway and increase RAD51 expression to maintain cell viability." (PMID 32316968, 2020). "Loss of PARP1 expression was not tolerated in cancer cells carrying a mutation in the BRCA1 gene." (PMID 32686903, 2020). "Therefore, the inhibition or silencing of PARP1 in cancer cells may prevent or at least reduce the M2 polarization of adjacent macrophages." (PMID 32900001, 2020). "Therefore, we hypothesize that targeting PARP1 might be a fruitful direction to sensitize BRCA1m cancer cells to chemotherapy." (PMID 31989039, 2020). "Thus, in cancer cells, PARP1 and PSAT1 inhibition could fail to promote changing in gene expression leading to cell death." (PMID 31105872, 2019). "Upon entry into the nucleus, cGAS interacts with PARP1 and inhibits the formation of PARP1-Timeless complex, thereby suppressing homologous recombination-mediated DNA repair and promoting tumorigenesis, indicative of cGAS as a novel therapeutic target for cancer." (PMID 30937856, 2019). "In the proband and affected brother, the Thr124Ala variant in PARP1 and the Thr535Ser variant in TRAP1 are of particular interest because like SDHA, these proteins impact mitochondrial function, and defects in PARP1 and TRAP1 have been associated with cancer risk or CAKUT." (PMID 30680959, 2019). "Finally, these cells seem to rely heavily on PARP1/2 for DNA repair, and treatment with the PARP1/2 inhibitor olaparib leads to synthetic lethality, suggesting that cancer cells with low KMT2C expression are attractive targets for therapies with PARP1/2 inhibitors." (PMID 30665945, 2019). "Olaparib, Niraparib, Veliparib, and Rucaparib that are in different phases of research and clinical trials for cancers including HGSC may be evaluated in the CCM-Class for PARP1 as a potential therapeutic target (ClinicalTrials.gov Identifier: NCT00535119, NCT00664781, and NCT00516373)." (PMID 30857227, 2019).
cancer (continued). "Theoretically, to increase efficiency of PARP1 inhibitors in cancer therapy, we could modulate the activity of proteins related to its function; this could enhance clinical utility of PARP inhibitors and give further clue to address the resistance to PARP inhibitors." (PMID 31105872, 2019). "Therefore, it might be possible to adapt PARP1 inhibitors for the modulation of intracellular processes in a wider range of cancers." (PMID 31614656, 2019). "Cancer cells use PARP1 to initiate a variety of DNA repair pathways, particularly BER and HR, to prevent cell death caused by the accumulation of cytotoxic DNA damage, making it a good candidate for sensitizing cancer cells to the cytotoxic effects of DNA damaging agents." (PMID 31500199, 2019). "Finally, PARP‐1‐driven expression of HR factors may be a potential determining factor in the anti‐cancer effects of PARP‐1 suppression through enhancing or inducing BRCA‐ness." (PMID 30467127, 2018). "Given PARP1 pleiotropic roles in aging, inflammation, degeneration and cancer, these systems may provide useful reagents for the future development of PARP inhibitors and other drugs that target innate immune signaling for the prevention and/or treatment of these disorders." (PMID 29590171, 2018). "In addition, the inhibition of MTH1 increased the response of cancer cells to the PARP-1 inhibitor." (PMID 29938005, 2018). "Therefore, there is growing interest in the application of PARP1 inhibitors in cancer treatment." (PMID 29306194, 2018). "Therefore, hypophosphorylation of retinoblastoma family members by the application of CDK4/6 inhibitors may suppress PARP1 transcription in fast growing cancer cells." (PMID 29306194, 2018). "Thus, although further verifications are required, sensitivity of cancer cell lines to PARP1 inhibitor may be a useful biomarker to predict efficiency of HR-mediated gene editing with the CRISPR/Cas9 system." (PMID 29967475, 2018). "Therefore, PARP1 has a vital role in the survival of damaged cells, and could confer a survival advantage to cancer cells during anti-cancer therapy targeting apoptosis of cancer cells." (PMID 29784019, 2018). "Our findings may have significant translational implications since aberrant EZH2 activity contributes to cancer and PARP1 inhibitors are in clinical trials, and we show that combinatorial treatment with an EZH2 and PARP1 inhibitor enhances PARP-mediated genotoxicity in cells from cancer patients." (PMID 29535829, 2018). "Thus, sensitivities of cancer cells to PARP1 inhibitors might be useful to evaluate their status of the HR pathway." (PMID 29967475, 2018). "However, to the best of our knowledge, whether lncRNAs take part in the increase in PARP1 expression in cancer remains unknown." (PMID 29776974, 2018). "Thus, inhibition of overexpressed PARP1 in human malignances may work on repressing chronic inflammatory-induced cancer progression, through blocking the NF-κB activation effect of PARP1." (PMID 28991194, 2017). "Because PARP1 is also involved in the repair of oxidative DNA damage, we next tested whether oxidative stress induced by berberine also contributes to the increased sensitivity of cancer cells to PARP inhibition." (PMID 28981112, 2017). "Metastasis may also link to PARP1-mediated chronic inflammation in carcinomas." (PMID 28991194, 2017). "Therefore, when considering that the expression of PARP1 is very predictive in the prognosis of STS patients, a combination of PARP1 inhibitor and genotoxic cancer therapeutic modalities might be effective in the treatment of STS patients." (PMID 27643881, 2016).